LINC00616 (long independently transcribed non-coding RNA 616)
Gene: Long non-coding RNA gene on chromosome 4 (137,967,479 to 138,131,182, reverse strand). Ensembl gene ENSG00000248307.
Diseases named in the same sentence as LINC00616 in open-access papers:
LINC00616 is named in the same sentence as 1 disease in open-access papers, as found by Europe PMC text mining. Sharing a sentence is not in itself a finding about the gene and the disease. The quoted sentences say what the papers report.
periodontitis (2 papers, 2022 to 2025). An acute or chronic inflammatory process that affects the tissues that surround and support the teeth. "LINC00616 is a newfound lncRNA aberrant expressed in periodontitis; however, the underlying mechanisms remain to be investigated." (PMID 35611986, 2022). "Meanwhile, LINC00616 was also significantly overexpressed in periodontal ligament tissues in patients with periodontitis compared with normal controls." (PMID 35611986, 2022). "Our study aimed to investigate the role of LINC00616 in the development of periodontitis." (PMID 35611986, 2022). "Knockdown of LINC00616 may be an alternative for the treatment of periodontitis." (PMID 35611986, 2022). "Interestingly, knockdown of LINC00616 accelerated cell viability and inhibited ferroptosis of periodontitis model cells, suggesting that inhibition of LINC00616 may alleviate the process of periodontitis." (PMID 35611986, 2022). "Additionally, LINC00616 not only downregulates the expression of GPX4 and SLC7A11 but also targets miR-370, indirectly influencing and enhancing the levels of TFRC, thereby promoting the occurrence of ferroptosis, LINC00616 knockdown may be a promising therapeutic strategy for periodontitis." (PMID 40454168, 2025). "Therefore, LINC00616 knockdown may be a promising therapeutic strategy for periodontitis." (PMID 35611986, 2022).